GABPA (GA binding protein transcription factor subunit alpha)
Diseases named in the same sentence as GABPA in open-access papers (continued):
Sharing a sentence is not in itself a finding about the gene and the disease.
clear cell renal cell carcinoma (2 papers, 2021 to 2022). "Also, lower expression of GABPA is associated with shorter 5-year survival in clear cell renal cell carcinoma and colorectal and head neck cancer based on TCGA database." (PMID 34306255, 2021). "The ETS transcription factor GABPA has long been thought of as an oncogenic factor and recently suggested as a target for cancer therapy due to its critical effect on telomerase activation, but the role of GABPA in clear cell renal cell carcinoma (ccRCC) is unclear." (PMID 35549739, 2022).
renal cell carcinoma (2 papers, 2022). "In UCBs, TCs and renal cell carcinomas (RCCs), GABPA or GABPB1 inhibition promotes their stemness and invasiveness, despite downregulation of TERT expression." (PMID 36713366, 2022).
breast tumor (1 paper, 2015). "The discovery of specific breast tumor subgroups using SAGS and the GABPA gene network was possible due to our original, biological knowledge-driven, genomic architecture-centered meta-analysis approach." (PMID 26517092, 2015).
endometrial carcinoma (1 paper, 2021). A malignant tumor arising from the epithelium that lines the cavity of the uterine body. "However, the function and clinicopathological significance of GABPA in endometrial carcinoma (EC) remain obscure." (PMID 34306255, 2021).
ulcerative colitis (1 paper, 2025). An inflammatory bowel disease involving the mucosal surface of the large intestine and rectum. "In this study, we identified FOXC1, GABPA, GATA2, and SUPT5H as key transcription factors implicated in the development of ulcerative colitis (UC) through the regulation of gene expression involved in inflammation, immune response, and epithelial barrier integrity." (PMID 41300749, 2025).
cancer (37 papers, 2011 to 2025). A tumor composed of atypical neoplastic, often pleomorphic cells that invade other tissues. "Like other tumor suppressors, the aberrant promoter hypermethylation and/or copy number loss contribute to the downregulation of GABPA or GABPB1 in the cancer types above." (PMID 36713366, 2022). "Our data showed that GABPA knockdown substantially reduced the recruitment of p-ERK to mutant TERT promoter in cancer cells carrying both BRAFV600E and TERT promoter mutations." (PMID 33483600, 2021). "Given that p-Sp1 and GABPA can be recruited to mutant TERT promoter with high cooperativity, thus we suppose that Sp1 and GABPA synergistically activate mutant TERT promoter in cancer cells carrying both BRAFV600E and TERT promoter mutations." (PMID 33483600, 2021). "The mutant TERT promoter is transcriptionally active and contains the H3K4me2/3 active chromatin mark and recruits the GABPA/B1 transcription factor, whereas in several cancer cell lines, the wild-type allele retains the H3K27me3 epigenetic silencing mark and is transcriptionally inactive." (PMID 35326649, 2022). "Additionally, dimethyl fumarate induces the apoptosis of cancer cells by inhibiting the induction of GABPA/PARK7 by mutated Kirsten rat sarcoma 2 viral oncogene homolog (KRAS)." (PMID 32357493, 2020). "The ETS transcription factor GABPA exhibits an oncogenic effect by activating telomerase in many cancers; however, some studies imply its tumor suppressive activities." (PMID 40813762, 2025). "Given all the oncogenic effects of TERT, GABPB1 and GABPA-mediated TERT upregulation is expected to promote cancer progression." (PMID 35326537, 2022). "Given the requirement of GABPA and GABPB1 to activate the mutated TERT promoter, they have been suggested as targets for telomerase-based cancer therapy." (PMID 36713366, 2022). "These unprecedented findings suggest that it should be cautious in targeting GABPA or GABPB1 for cancer intervention." (PMID 35549739, 2022). "On the other hand, the strong association between GABPA and TGFBR2 is observed in many types of cancer based on the TCGA data analyses, which indicates a broad implication of the present findings in oncogenesis." (PMID 35549739, 2022). "Among these TFs, GABPA was most frequently enriched in the common region at BRCA1 promoter in five cancer cell lines and liver tissues." (PMID 32000125, 2020). "Mechanistically, we identified DICER1, a component of the microRNA machinery to inhibit cancer metastasis, as a direct target gene for GABPA." (PMID 31285550, 2019). "This discrepancy with regard to the role of GABPA as both promoter and suppressor of cancer aggressiveness warrants further investigation." (PMID 31200515, 2019). "In cancer cells carrying heterozygous TERT promoter mutations, the mutant promoter recruits GABPA and exhibits the H3K4me2/3 mark of active chromatin." (PMID 31285550, 2019). "According to the model suggested by these authors, GABPA exerts a potent anti-metastatic function by directly stimulating the expression of Dicer1, a master suppressor of cancer initiation and progression." (PMID 31200515, 2019). "The mechanism of reactivation of telomerase in cancers has been recently reported to take place by recruitment of transcription factor such as GABPA or BRAF specifically to mutant TERT promoters, hence driving TERT transcription." (PMID 29907642, 2018). "However, our findings reveal inhibitory effects of GABPA on the progression of several cancer types." (PMID 40813762, 2025). "GABPA has long been shown as an oncogenic driver, and especially the recent identification of its role in telomerase activation has led to the proposal to target it for cancer therapy." (PMID 40813762, 2025). "The role for GABPA in oncogenesis is context or cancer-type-dependent." (PMID 40813762, 2025).
cancer (continued). "Since the hotspot mutations in TERT promoter had been well accepted to create de novo binding sites for GABPA/GABPB complex, most of previous studies aiming at targeting mutant TERT in human cancers were focused on targeting GABPA and/or GABPB directly or indirectly." (PMID 38769666, 2024). "Evidently, the loss of GABPB1 or GABPA is a more potent cancer-driving force that compensates for the lack of TERT upregulation." (PMID 35326537, 2022). "Furthermore, we confirmed that de novo methylation is precluded across cancers at CpGs lying in genomic regions enriched for TF binding signatures associated with SP1, CTCF, NRF1, GABPA, KLF9, and/or YY1." (PMID 35440061, 2022). "Therefore, targeting GABPB1 or GABPA for telomerase-based therapy has been suggested as a novel anti-cancer strategy." (PMID 35549739, 2022). "We therefore hypothesized that serum starvation-induced changes in GABPA and GABPB1 could underlie the relationship between cell proliferation and the regulation of TERT, specifically in TERTp-mutant human cancer cells." (PMID 36130485, 2022). "However, evidence has recently accumulated that GABPA function may be context-dependent, and it acts as a tumor suppressor in several types of cancer, despite its stimulatory effect on TERT transcription." (PMID 35549739, 2022). "Moreover, transcription is driven by recruitment of the transcription factor GA binding protein transcription factor subunit alpha (GABPA) and subunit beta (GABPB) to the mutated promotor, leading to an increased transcription of the mutated TERT allele in cancer cells." (PMID 34680452, 2021). "Finally, we sought to probe the mechanism of GABPA downregulation in cancers." (PMID 34306255, 2021). "However, the current mechanisms of GABPA on cancer initiation and progression are inconsistent." (PMID 34306255, 2021). "Whether GABPA could serve as a therapeutic target for cancer?" (PMID 31285550, 2019). "However, studies on the role of GABPA in human cancer are rare, and whether GABPA is involved in HCC cell invasion and migration remains unclear." (PMID 28549418, 2017). "Therefore, the effect of GABPA on cancer cell migration and invasion may be cancer and tissue specific and may involve different signaling pathways in different cells." (PMID 28549418, 2017). "These DNAm sites were mapped to genes that play mechanistic roles in multiple cancers, such as cg06513015 on ERV3-1, cg09516963 on DYRK2, cg26919182 on PPP1R12B, and cg17612569 on GABPA and ATP5J." (PMID 36966332, 2023). "Given that the ETS family transcription factors GABPA and GABPB1 activate the mutant TERT promoter and induce TERT expression for telomerase activation, GABPB1 has been proposed as a cancer therapeutic target to inhibit telomerase." (PMID 35326537, 2022). "While the emCpGs harbour enriched binding sites for their specific emTFs, the non-correlated CpGs shared a binding signatures for SP1, CTCF, NRF1, GABPA, KLF9, and YY1 providing a protective effect against de novo methylation across cancer types." (PMID 35440061, 2022). "Collectively, GABPA and GABPB1 functions are context- or cell type-dependent, and caution should be taken to target them for telomerase-based cancer therapy." (PMID 36713366, 2022). "Taken together, our data indicate that GABPA and Sp1 synergistically activate mutant TERT promoter, contributing to tumorigenesis and cancer progression, particularly in the BRAFV600E-driven human cancers." (PMID 33483600, 2021). "The CNV or DNA methylation levels of some genes have been reported to regulate the expression of these genes in multiple cancer types, such as FBP1 in LIHC, GABPA in BLAC." (PMID 34222028, 2021). "The top 5 important TFs observed in more than 10% of all cancer genomes include SP1, RXRA, NR2F2, GABPA, and CTCF." (PMID 33647036, 2021).
cancer (continued). "The expression of miR-378* increases duringbreast cancer progression and miR-378* induces the Warburg effect in breastcancer cells by inhibiting the expression of two PGC-1 partners, ERR and GABPA." (PMID 21436881, 2011). "Several studies have previously investigated the roles of CCND1, GABPA, HIF1A, and SOX6 in various diseases, including cancer and cardiovascular diseases, but the specific roles of these genes in HF and their interaction within the context of the PI3K/AKT pathway have not been well-explored." (PMID 40818967, 2025). "By analyzing differentially expressed miRNAs between GABPA-high and low tumors in the TCGA BLCA cohort, we observed that miR-30e was among the top ones that positively correlated with GABPA expression, while miR-30e has been shown to target P4HA2 in several cancer types." (PMID 40813762, 2025). "In addition, iHerd highlighted GABPA, a TF selectively recruited to the mutant form of the TERT promoter to activate TERT’s transcription in most human cancers." (PMID 37695793, 2023). "Concerning transcription factors, sets of the most important features are less similar to each other for different cancer types but nevertheless CTCF, GABPA, RXRA, SP1, MAX and NR2F2 are more frequently included in top features than other transcription factors." (PMID 33647036, 2021). "Consistently, inhibiting the expression of GABPA or GABPB1 rather than other ETS members led to diminished TERT expression in cancer cells bearing a mutant TERT promoter." (PMID 31285550, 2019). "Whether the effects of GABPA on the wt TERT promoter and cancer development/progression are context-dependent?" (PMID 31285550, 2019). "In these types of cancer, miR-378 seemed to be an oncogene, and enhanced tumor cell survival, promoted tumor growth and metastasis in some tumors via regulation of the target genes SuFu, Fus-1, HMOX1, ESRRG and GABPA." (PMID 24555885, 2014). "Finally, the GABPA function may be species- and context-dependent, and it is thus essential to thoroughly delineate the full spectrum of roles for GABP factors in given cancer types for precision oncology." (PMID 31802036, 2020). "However, GABPA and GABPB1 stimulate TERT transcription, but several lines of evidence suggest that they may serve as tumor suppressors in other cancer types regardless the presence or absence of TERT promoter mutations." (PMID 36713366, 2022).
tumor (30 papers, 2014 to 2025). "In multiple types of tumor cells, GABPA can selectively bind to the ETSdomain of the mutated telomerase reverse transcriptase (TERT) promoter and activate its transcription." (PMID 36042907, 2022). "The hTERT promoter is often a subject to activatory mutations in neoplasia which facilitate its activation by GABPA and other ETS family transcription factors." (PMID 32545208, 2020). "The selective binding of GABPA to mutant promoter was confirmed in vivo and extended to different tumor settings by the analysis of ChIP-seq data from ENCODE project." (PMID 31200515, 2019). "Consistent with the tumor suppressive role of GABPA in cells, GABPA downregulation was associated with aggressive clinicopathological characteristics in HCC patients." (PMID 28549418, 2017). "Increasing evidence indicates that abnormal expression of GABPA is associated with tumor development and progression." (PMID 28549418, 2017). "Because tumor suppressors are generally silent by DNA methylation and/or genetic deletion/mutation, we determined whether this was the case for the downregulated GABPA expression in BCs." (PMID 31802036, 2020). "All these injected cells formed tumor foci in lungs (except one mouse injected with J82/GABPA cells), but their numbers differed substantially." (PMID 40813762, 2025). "Like other tumor suppressors, the aberrant GABPA promoter methylation occurs frequently in BCs and RCCs, which leads to its downregulation in these tumors." (PMID 40813762, 2025). "The tumor number in lungs derived from J82 cells overexpressing both GABPA and P4HA2 was almost the same as that of J82/vector cells." (PMID 40813762, 2025). "Although GABPA-mediated TERT induction and telomerase activation are required for BC development/progression, we recently unraveled that GABPA itself inhibited BC cell proliferation and invasion, suggesting its tumor suppressive function." (PMID 40813762, 2025). "In 31 ccRCC patients whose tumor specimens and NTs were available, qPCR results unexpectedly revealed that GABPA mRNA levels were significantly lower in most tumors (22/31) than in NTs." (PMID 35549739, 2022). "We also measured the mRNA expression of the GABP TF complex subunits, GABPB1 and GABPA, which shows detectable and robust expression in all available tumor regions." (PMID 36114166, 2022). "Tumors grew significantly slower in mice harboring 786-O/GABPA cells and tumor sizes were only 15% of those derived from 786-O/control cells." (PMID 35549739, 2022). "The DNA hypermethylation similarly occurs in the GABPA promoter, which leads to the diminished GABPA expression, thereby attenuating its tumor suppressor function." (PMID 35326537, 2022). "Intriguingly, the presence of TERT promoter mutations represents a featured hallmark for aggressive TCs whereas GABPA and GABPB1 expression is downregulated in those tumours." (PMID 36394204, 2022). "A recent study showed that GABPA has tumor suppressor properties in thyroid tumors, rendering this factor an unadvisable target for inhibition in this lineage." (PMID 35053525, 2022). "GABPA is a downstream target of the androgen receptor in PCa and enables the tumor cells to become more aggressive." (PMID 34879849, 2021). "ChIP-Seq data also demonstrate that in SK-N-SH or HEPG2 tumor cells GABPA is present at the TERT promoter region." (PMID 33257697, 2020). "Intriguingly, it was recently reported that GABPA controls the cell cycle and induces cell differentiation, thus acting as a tumor suppressor regulating cell proliferation, stemness, and adhesion." (PMID 32204305, 2020). "Decreased GABPA expression was correlated with alpha-fetoprotein levels (P = 0.001), tumor grade (P = 0.017), and distant metastasis (P = 0.021)." (PMID 28549418, 2017). "As poor prognosis of HCC patients is mainly related to tumor migration, we further examined the effect of GABPA on the invasive properties of HCC cells." (PMID 28549418, 2017).
tumor (continued). "Secondly, HCC patients were followed-up and the 54 patients were divided into two groups according to the mRNA expression levels of GABPA as follows: high-GABPA (n = 21, with higher GABPA mRNA level compared with paired non-tumor) and low-GABPA (n = 33)." (PMID 28549418, 2017). "On the basis of the biological function of E-cadherin in HCC tumor metastasis, we examined the expression of E-cadherin in GABPA knockdown cell lines by western blotting and real-time PCR." (PMID 28549418, 2017). "The downregulation of GABPA in human HCC tissues and cell lines suggested that GABPA functions as a tumor-suppressor in HCC." (PMID 28549418, 2017). "One possible explanation is that as a transcription factor, GABPA may be involved in regulation of various downstream genes; therefore, the way GABPA acts may depend on the type of tumor and its specific cellular microenvironment and signaling pathways." (PMID 39759007, 2024). "Moreover, in primary TC tumours, there is a significantly inverse correlation between GABPA and TERT gene expression." (PMID 36394204, 2022). "Taken together, GABPA was a tumor suppressor that inhibited migratory potential in GC through negatively regulating GPX1, which could be utilized in the clinical targeted therapy of GC." (PMID 36042907, 2022). "Thus, GABPA functions as a tumor suppressor in ccRCC and oncometabolite-mediated epigenetic silencing of GABPA is a critical driver event in the ccRCC progression." (PMID 35549739, 2022). "The expression of GABPA was higher in HCC compared with non-tumor tissues in TCGA-LIHC." (PMID 35958019, 2022). "Serving as a tumor suppressor, GABPA blocks GC cells to migrate by targeting GPX1." (PMID 36042907, 2022). "Recent studies implied a complicated relationship between GABPA and tumor progression." (PMID 34306255, 2021). "One of potential explanations is that GABPA is a transcription factor and may regulate various downstream genes, so, how GABPA works may depend on different cell contexts and tumor types." (PMID 34306255, 2021). "Both J82/Control and J82/GABPA cells formed metastatic nodules in mouse livers but rarely in lungs; However, the number of tumor colonies were substantially fewer in livers from mice harboring J82/GABPA cells (J82/Control vs J82/GABPA: 15 ± 5/liver vs 3 ± 1/liver, P = 0.041)." (PMID 31802036, 2020). "The present findings thus suggest that GABPA acts a tumor suppressor in BC." (PMID 31802036, 2020). "It is evident from all these observations that GABPA exhibits a tumor suppressive function in BC." (PMID 31802036, 2020). "Knockdown of GABPA significantly downregulated E-cadherin in transplanted tumor tissues." (PMID 28549418, 2017). "GABPA may act as a tumor suppressor during HCC progression and metastasis, and is a potential therapeutic target in HCC." (PMID 28549418, 2017). "This suggests that GABPA might be a key regulator of inflammation in the tumor microenvironment." (PMID 40818967, 2025). "Therefore, the present study points out that GABPA may act as a tumor suppressor, and it could be considered as a potential prognostic biomarker for EC." (PMID 34306255, 2021). "Therefore, the relationship between the mutant TERT promoter and GABPA is more complicated than expected, and GABPA may act as either a tumor-driver or suppressor in context-dependent manners." (PMID 31802036, 2020). "Therefore, GABPA may serve as a tumor suppressor in BCs and a useful biomarker in BC prognostication and management decisions." (PMID 31802036, 2020). "GABPA-overexpressed cells generated the fewest foci, while P4HA2 overexpression induced 2-fold higher numbers of tumor cell seeding, compared to control J82 cells with an empty vector (J82/vector)." (PMID 40813762, 2025). "Several lines of evidence suggest that GABPA and GABPB1 serve as tumour suppressors to inhibit TC aggressiveness." (PMID 36394204, 2022). "Thus, it is speculated that GABPA could be a tumor suppressor involved in the progression of GC." (PMID 36042907, 2022).